CRP (C-reactive protein)
Diseases named in the same sentence as CRP in open-access papers (continued):
Sharing a sentence is not in itself a finding about the gene and the disease.
leukocytosis (continued). "Laboratory tests showed leukocytosis (WBC 14,510/μL; normal 4000–11,000/μL), neutrophils 70.8% (normal 37.5–77%), and elevated CRP (35.8 mg/L; normal < 5)." (PMID 41283341, 2025). "Laboratory findings showed leukocytosis (WBC 14,290/μL; normal 4000–11,000/μL), neutrophilia (94.3%; normal 40–74%), and elevated C-reactive protein (CRP 121 mg/L; normal < 5)." (PMID 41283341, 2025). "Initial blood work demonstrated a markedly elevated C-reactive protein (CRP) at 119 mg/L, along with leukocytosis (WBC 15 × 109/L, with neutrophils 12.3 × 109/L)." (PMID 40989532, 2025). "A 43-year-old presented with wheezing, multifocal neuropathy, leukocytosis, eosinophilia, positive ANA, and elevated CRP." (PMID 40597425, 2025). "At initial presentation, all patients showed leukocytosis (WBC: 13.41–28.2 × 10^9/L), thrombocytosis (PLT: 359–594 × 10^9/L), anemia (HGB: 62–110 g/L), and elevated inflammatory markers (CRP: 100–166.68 mg/L; ESR: 19–112 mm/h; IL-6: 32.51–58.4 pg/mL)." (PMID 40859316, 2025). "Initial laboratory investigations demonstrated leukocytosis (WBC 19.66 × 109/L), markedly elevated C-reactive protein (CRP, 266.04 mg/L) and procalcitonin (PCT, 12.87 ng/mL), hypoxemia (pO2, 68 mmHg), and elevated lactate levels (4.2 mmol/ L)." (PMID 40672036, 2025). "Laboratory studies demonstrated leukocytosis (WBC 15.1 × 109/L) and anemia (hemoglobin 9.4 g/dL), with markedly elevated inflammatory markers (C-reactive protein (CRP) 113.5 mg/L)." (PMID 41164077, 2025). "Initial laboratory tests revealed leukocytosis (WBC 21,600/μL; band 3%, segmented neutrophils 86%), elevated C-reactive protein (CRP 33.1 mg/dL), procalcitonin 3.4 ng/mL, anemia (Hb 9.6 g/dL), and acute kidney injury (Cr 1.4 mg/dL, baseline ~1.0 mg/dL)." (PMID 41010278, 2025). "Laboratory studies showed leukocytosis with a white blood cell (WBC) count of 14,100/μL (neutrophils 89.6%) and an elevated C-reactive protein (CRP) level of 11.04 mg/dL." (PMID 41158892, 2025). "Laboratory investigations at admission showed leukocytosis with a white blood cell (WBC) count of 20,110/mm3, hemoglobin (Hb) of 15 g/dL, and an elevated C-reactive protein (CRP) level of 274 mg/L." (PMID 40276410, 2025). "On February 5, laboratory tests showed leukocytosis (WBC 13.79 × 109/L), neutrophilia (GRAN 95.8%), and elevated C-reactive protein (CRP 187.30 mg/L)." (PMID 41035666, 2025). "Case-2 laboratory testing upon admission revealed leukocytosis (WBC 21,760/μL) and elevated CRP (295.9 mg/L)." (PMID 41011403, 2025). "Imaging revealed right upper lobe consolidation, and laboratory evaluation showed leukocytosis (WBC 29K), hyponatremia (Na 130 mEq/L), and elevated CRP (215.9 mg/L)." (PMID 40201874, 2025). "Laboratory findings revealed elevated C-reactive protein (CRP) and erythrocyte sedimentation rate (ESR), along with mild leukocytosis." (PMID 41458268, 2025). "Leukocytosis (WBC: 15 × 109/L, neutrophils: 12.3 × 109/L), Hemoglobin: 110 g/L, platelets normal, elevated CRP (119 mg/L, subsequently reducing to 57 mg/L)." (PMID 40989532, 2025). "Laboratory markers such as CRP, LDH, leukocytosis, and thrombocytopenia are valuable indicators of disease severity." (PMID 41294908, 2025). "From a laboratory perspective, our patient demonstrated significant systemic inflammation at presentation, with leukocytosis (WBC 12.7 × 103/μL), thrombocytosis (platelets 578 × 103/μL), elevated C-reactive protein (172 mg/L), and an ESR of 105 mm/hr." (PMID 41234999, 2025). "Laboratory tests revealed leukocytosis of 12.8 ×109/L (reference: 4.0-9.0 ×109/L), elevated ESR of 38 mm/h (reference: <15 mm/h), and C-reactive protein of 52 mg/L (reference: <5 mg/L)." (PMID 41210013, 2025). "Elevated CRP in 34 (85%) patients, raised ESR in 31(78%) patients, thrombocytosis in 18(45%), anaemia in 17 (43%) and leukocytosis in 15(38%) patients." (PMID 41042754, 2025). "High C-Reactive protein (CRP > 10 mg/dl), thrombocytosis, anaemia and leukocytosis were 85%, 45%, 43%, 38% respectively." (PMID 41042754, 2025).
leukocytosis (continued). "Laboratory investigations revealed leukocytosis (WBC 14.1×109/L), neutrophilia (13.0×109/L), and markedly elevated C-reactive protein (CRP) (226 mg/L)." (PMID 41262842, 2025). "Repeat labs showed leukocytosis (white blood cell count—WBC 30.46 × 109/L–30.460/μL), C-reactive protein (CRP) 36.12 mg/L, and procalcitonin (PCT) 0.25 ng/mL." (PMID 41041452, 2025). "Laboratory studies demonstrated leukocytosis (white blood cell (WBC) 12.8×109/L), elevated C-reactive protein (CRP) (159 mg/L), and anaemia (haemoglobin (Hb) 87 g/L)." (PMID 41552222, 2025). "Laboratory abnormalities usually pertain to elevated acute-phase reactants like elevated erythrocyte sedimentation rate (ESR), C-reactive protein (CRP), or leukocytosis." (PMID 40718241, 2025). "The investigation revealed leukocytosis, with a total count of 14,370/cumm (normal range 4,000-10,000/cumm) and CRP (C-reactive protein) of 15.39 mg/L (normal range <6 mg/L)." (PMID 40959332, 2025). "Laboratory tests indicated leukocytosis with neutrophilia (WBC 14.75 × 103/μL, neutrophils 75%) and elevated C-reactive protein (CRP 149.71 mg/L)." (PMID 40077047, 2025). "Laboratory evaluation demonstrated leukocytosis (WBC: 16,400/μl) and a markedly increased C-reactive protein (CRP) level (63 mg/L), consistent with systemic inflammation." (PMID 40922880, 2025). "Labs are significant for elevated C-reactive protein (CRP) (9.9) and erythrocyte sedimentation rate (ESR) and significant leukocytosis (22.5) with a neutrophilic predominance (74%)." (PMID 40718232, 2025). "Laboratory findings are nonspecific but typically reflect systemic inflammation, including elevated erythrocyte sedimentation rate (ESR), C-reactive protein (CRP), leukocytosis, normocytic anemia, and thrombocytosis." (PMID 40837553, 2025). "Biological tests showed an elevated C-reactive protein (CRP) level of 44.7 mg/L, leukocytosis (14×109/L), plateletosis (44x109/L), acute kidney injury was noted, with a creatinine level of 1.93 mg/dL and a glomerular filtration rate of 25 mL/min/1.73m2." (PMID 40255855, 2025). "Initial laboratory tests revealed leukocytosis (WBC 11.92 × 109/L) with marked neutrophilia (87.2%) and an elevated C-reactive protein level (104.69 mg/L)." (PMID 41488077, 2025). "Laboratory tests revealed increased inflammatory markers: increased serum C-reactive protein (CRP; 176.53 mg/L), leukocytosis [white blood cells (WBCs), 13.9 × 109/L], and an elevated erythrocyte sedimentation rate (ESR; 47 mm/h)." (PMID 41235243, 2025). "Laboratory analysis showed leukocytosis (WBC 19.8 × 109/L, 90th percentile), elevated C-reactive protein (CRP) (11.8 mg/L; normal: <5), normocytic anemia (HGB: 93 g/L; normal: 110–140 g/L, and critical hyponatremia (Na+: 117 mmol/L; normal: 135–145 mmol/L)." (PMID 41278037, 2025). "Laboratory tests showed leukocytosis (WBC: 36.23 × 109/L, neutrophils 94%), thrombocytosis (536 × 109/L), anemia (Hb: 88 g/L), and an elevated C-reactive protein (CRP) of 287.56 mg/L." (PMID 41000184, 2025). "Laboratory investigations showed markedly elevated C-reactive protein (CRP) and leukocytosis with neutrophilia, alongside severe lymphopenia." (PMID 41209958, 2025). "In OM patients, leukocytosis (WBC count > 12000) was present in 57.9% of cases, 52.6% had an ESR > 40 mm/h, and 68.4% had elevated CRP levels (qualitative values of 1 + or higher and quantitative values of 20 mg/L or higher)." (PMID 41366651, 2025). "Laboratory tests showed leukocytosis with a WBC count of 30.53 × 109/L, neutrophil count of 20.22 × 109/L, and elevated C-reactive protein (CRP) at 131.39 mg/L." (PMID 41341106, 2025). "Evaluation of the patients' classic laboratory findings revealed leukocytosis (WBC ≥ 12 000/mm3) in 12 (50%), elevated CRP ((≥ 5 mg/L) L) in 17 (70.8%), and elevated ESR (≥ 20 mm/h) in 12 (50%)." (PMID 40590520, 2025).
leukocytosis (continued). "Common laboratory findings are hyperbilirubinemia, anemia, leukocytosis, and increased levels of ALP, AST, GGT, ALT, CRP, total bilirubin, and conjugated bilirubin." (PMID 40731941, 2025). "Laboratory tests revealed significantly elevated inflammatory markers (CRP 78 mg/L, ESR 33 mm/h) and leukocytosis (11,980/μL with 78 % PMNs), confirming an active infection." (PMID 40132526, 2025). "Laboratory tests demonstrated leukocytosis, elevated ESR and C-reactive protein, and anemia, consistent with infection and inflammation." (PMID 41210013, 2025). "Laboratory tests revealed leukocytosis with neutrophilia (WBC 13.60 × 109/L, NEU 83.4%) and a mildly elevated C-reactive protein (CRP 6.16 mg/L), while liver enzymes, kidney function, lipase, and electrolyte levels were within normal limits." (PMID 41153265, 2025). "Laboratory investigations showed leukocytosis (WBC 18,000/mm3), elevated C-reactive protein (CRP 65 mg/L), mild electrolyte imbalance (hypokalemia, hyponatremia), and moderate anemia (Hb 10.2 g/dL)." (PMID 40869648, 2025). "Laboratory tests demonstrated leukocytosis (WBC count: 11.78 × 109/L), neutrophilia (NEUT count: 8.06 × 109/L), and elevated C-reactive protein (CRP) levels (244.75 mg/L)." (PMID 40880771, 2025). "Laboratory results revealed significant leukocytosis (WBC: 38.65 × 103/μL), markedly elevated CRP (302 mg/L), and normal immunoglobulin levels (IgA: 194 mg/dL, IgG: 1010 mg/dL, and IgM: 164 mg/dL)." (PMID 40708794, 2025). "Other laboratory abnormalities associated with Legionella include hyponatremia, hypophosphatemia, leukocytosis, elevated ESR and CRP, and, in some cases, myoglobinuria." (PMID 40247848, 2025). "Bacterial CAP is characterized by crackles or asymmetric breath sounds, slow onset of symptoms, prolonged fever, increased inflammatory markers, elevated CRP and PCT, leukocytosis and neutrophilia." (PMID 40806926, 2025). "The initial laboratory findings revealed leukocytosis (22,750 WBC/mm3) with an elevated neutrophil count (19,565/mm3), high C-reactive protein (CRP) at 97.1 mg/L, and an erythrocyte sedimentation rate (ESR) of 60 mm/h." (PMID 40149032, 2025). "Laboratory tests at that time revealed leukocytosis (white blood cell count [WBC] 11.7 × 10^9/L, neutrophil count 10.03 × 10^9/L), elevated C-reactive protein (CRP 113.9 mg/L), and lactate dehydrogenase (LDH 523 U/L)." (PMID 39931557, 2025). "Initial labs were notable for leukocytosis (white blood cells (WBC) 16,000 x 109/L) with a left shift (69% segmented neutrophils, 5% bands), elevated CRP (16.7 mg/dL), lipase 152 U/L, and a normal lactic acid (1.6 mmol/L)." (PMID 41257102, 2025). "As in our patient, laboratory findings are significant for elevated inflammatory markers such as leukocytosis, elevated erythrocyte sedimentation rate (ESR), and C-reactive protein (CRP)." (PMID 40981142, 2025). "Serial laboratory investigations revealed leukocytosis (WBC: 9.2 × 109/L), elevated inflammatory markers (CRP: 46.1 mg/L), and moderate anemia (HGB: 65 g/L)." (PMID 41278037, 2025). "In SA patients, leukocytosis was present in 50% of cases, 54.3% had an elevated ESR, and 80.4% had elevated CRP levels." (PMID 41366651, 2025). "Results indicate markedly elevated C-reactive protein (CRP), leukocytosis (white blood cell (WBC): 17.5×103/μL), and elevated liver enzyme alanine transaminase (ALT), suggestive of active inflammation and possible infection." (PMID 40951063, 2025). "CDS is primarily associated with advanced age and typically presents with neck pain, fever, and elevated inflammatory markers, such as C-reactive protein (CRP), erythrocyte sedimentation rate (ESR), and leukocytosis." (PMID 40027036, 2025). "Laboratory tests showed leukocytosis (white blood cell (WBC) count: 19,100/μL) and elevated C-reactive protein (CRP: 3.72 mg/dL)." (PMID 40831843, 2025).
leukocytosis (continued). "Laboratory investigations revealed marked leukocytosis (mean WBC: 18,505.6 ± 7,391.8 cells/mm3), elevated C-reactive protein (169 ± 68.7 mg/L), and increased creatinine levels (1.82 ± 0.7 mg/dL)." (PMID 40491633, 2025). "At the outpatient follow-up on POD 14, laboratory tests revealed leukocytosis (WBC 10,300/μL) and elevated C-reactive protein (CRP 3.83 mg/dL), suggestive of infection." (PMID 41322736, 2025). "Secondary outcomes were a reduction in lymph node size, tenderness, leukocytosis, erythrocyte sedimentation rate (ESR), and C-reactive protein (CRP)." (PMID 40351912, 2025). "A leukocytosis (WBC 14.5 × 109/L), anemia (hemoglobin: 10.6 g/dL), and a significantly elevated C-reactive protein (CRP: 187 mg/L) were observed in the laboratory investigations." (PMID 41280306, 2025). "Laboratory findings included leukocytosis (WBC 13.1 × 10^9/L), hyponatremia (Na 131 mmol/L), elevated C-reactive protein (19.1 mg/L), and hypoalbuminemia (3.3 g/dL)." (PMID 40125169, 2025). "Laboratory tests showed leukocytosis (WBC, 13,083/μL; neutrophils, 79.2%), mild elevation of C-reactive protein (CRP) and creatinine, and elevated CYFRA 5.2 ng/mL." (PMID 41312070, 2025). "Initial laboratory tests showed leukocytosis of 13,000 cells, a hemoglobin level of 11 gram/dL, an erythrocyte sedimentation rate (ESR) of 120 mm/h, and a C-reactive protein (CRP) level of 141 mg/L (normal lab value <3)." (PMID 40687924, 2025). "The patient had previously been hospitalized at a local facility where laboratory tests revealed leukocytosis (WBC 33.48 × 109/L), neutrophilia (84.6%), and elevated C-reactive protein (CRP 92.65 mg/L)." (PMID 41204570, 2025). "Laboratory evaluation revealed leukocytosis (white blood cell (WBC) 14.28 ×103/μL) with neutrophilic predominance, along with elevated inflammatory markers, including a C-reactive protein (CRP) of 4.1 mg/L and erythrocyte sedimentation rate (ESR) of 49 mm/hr." (PMID 41583236, 2025). "Main findings were thrombocytopenia, leukocytosis with neutrophilia, hemoconcentration, hyperlactatemia, hypoalbuminemia, elevated serum lactate dehydrogenase (LDH), creatine kinase (CK), and C-reactive protein (CRP)." (PMID 40979895, 2025). "Laboratory results revealed leukocytosis (white blood cell count (WBC) 17,000/μL) and elevated C-reactive protein." (PMID 41194835, 2025). "Laboratory investigations revealed a reactive C-reactive protein (CRP), a mildly elevated erythrocyte sedimentation rate (ESR) of 25 mm/hr, and +2 leukocytosis on urinalysis." (PMID 40313350, 2025). "The initial laboratory assessment revealed severe anemia [hemoglobin (Hb) = 60 g/L], concurrent leukocytosis [white blood cell (WBC) = 10.36 × 109/L), and a markedly elevated C-reactive protein (CRP = 64.21 mg/L)." (PMID 41568379, 2025). "The persistent, marked leukocytosis (WBC: 38.65 × 103/μL) and extremely elevated CRP (302 mg/L) signaled uncontrolled sepsis and overwhelming systemic inflammation, contributing to a state of persistent hematologic/inflammatory dysregulation." (PMID 40708794, 2025). "Additional investigations and findings that support the diagnosis include high inflammatory markers (CRP and/or ESR), leukocytosis, anemia, thrombocytopenia, and echocardiogram findings." (PMID 39877780, 2024). "Laboratory studies were significant for leukocytosis and elevated erythrocyte sedimentation rate (ESR) and C-reactive protein (CRP)." (PMID 39114221, 2024). "Laboratory data showed mild leukocytosis, mild anemia, and eosinophilia with increased erythrocyte sedimentation rate (ESR) and C-reactive protein (CRP)." (PMID 39233673, 2024). "The patient had anemia with hemoglobin at 6.0 and mild leukocytosis at 13.1 but had a normal erythrocyte sedimentation rate (ESR) and C-reactive protein (CRP)." (PMID 39347296, 2024). "Hematological investigations showed microcytic hypochromic anemia, leukocytosis, eosinophilia, and thrombocytosis with elevated ESR and CRP." (PMID 39867099, 2024).
leukocytosis (continued). "Laboratory investigations at the time of admission revealed leukocytosis (WBC: 18,200/μl), anemia (Hb: 9.8 g/dl), platelet count of 223,000/μL, and a mildly elevated C-reactive protein (CRP) level of 0.64 mg/dl." (PMID 39371863, 2024). "Upon admission to our hospital, blood tests revealed leukocytosis (WBC 17,030/μL) and thrombocytosis (Platelet 757 K/μL), elevated ESR (74 mm/h), and C-reactive protein (CRP) (5.1 mg/dL)." (PMID 38905364, 2024). "Laboratory tests showed elevated inflammatory parameters: C-reactive protein (CRP) 72 mg/l and leukocytosis in peripheral blood." (PMID 39781149, 2024). "Laboratory results indicated that cardiac troponin levels were elevated in 70% of patients, CK-MB levels in 55%, CRP levels in 40%, ESR levels in 35%, and leukocytosis in 25% of patients." (PMID 39360084, 2024). "Laboratory tests showed leukocytosis of 14 600 μl of white blood cells (WBC), elevated C-reactive protein (CRP) of 18 μg/ml (normal <0.3 μg/ml), and an elevated erythrocyte sedimentation rate (ESR) of 18 mm/h (normal <15 mm/h)." (PMID 39664272, 2024). "Laboratory tests revealed leukocytosis (11,000/uL with a predominance of neutrophils), an erythrocyte sedimentation rate (ESR) of 120 mm, C-reactive protein (CRP) of 10.3 mg/dL, and procalcitonin of 1.13 mg/dL." (PMID 39830536, 2024). "Laboratory tests and a CT scan for further evaluation revealed subcutaneous inflammation in the right upper thigh, leukocytosis with a WBC count of 12,900/μL, neutrophilia (92.5%), elevated CRP levels (up to 16.5 mg/dL), and an increased ESR (53 mm/h)." (PMID 39310601, 2024). "Features of systemic inflammation such as elevated C-reactive Protein (CRP), fever, and peripheral leukocytosis are often observed in ICH patients and are associated with worse clinical outcomes." (PMID 38645743, 2024). "During attacks, an elevation of acute phase reactants in the blood (serum amyloid A (SAA), C-reactive protein (CRP) and leukocytosis) can be detected." (PMID 39618694, 2024). "Laboratory tests showed in blood count that leukocytosis, neutrophilia, and lymphopenia high levels of ESR, CRP, ferritin, D-dimers, LDH, and Il-6 increased transaminase activity." (PMID 38543912, 2024). "Laboratory evaluation in TA reveals normochromic, normocytic anaemia, leukocytosis, thrombocytosis, elevated ESR, CRP, and raised ferritin." (PMID 38933629, 2024). "Leukocytosis (WBC counts ≥10,000/mm3) is noted in 14% of EN cases, and CRP elevation over 12 mg/dL is observed in only 13% of EN cases." (PMID 39310601, 2024). "Lab results showing microcytic hypochromic anemia, leukocytosis, eosinophilia, and thrombocytosis with elevated ESR and CRP." (PMID 39867099, 2024). "Blood examination revealed a slight elevation of C-reactive protein (CRP), glutamate oxalate transaminase (GOT), glutamate pyruvate transaminase (GPT), and lactate dehydrogenase (LDH), marked leukocytosis and mild anemia." (PMID 39781309, 2024). "The lab tests showed leukocytosis, elevation in liver enzymes (AST and ALT), and c-reactive protein (CRP)." (PMID 39861800, 2024). "Elevated C-reactive protein (CRP), lactate, and leukocytosis raise concerns for colonic ischemia as an important possible complication of Ogilvie syndrome to be considered, especially in elderly or those with bowel ischemia risk factors." (PMID 39711822, 2024). "Case 4 had leukocytosis, elevated erythrocyte sedimentation rate (ESR), and elevated C‐reactive protein (CRP)." (PMID 38411294, 2024). "Laboratory tests showed mild leukocytosis, elevated erythrocyte sedimentation rate (ESR), and C-reactive protein (CRP), which led to the diagnosis of immune-mediated arthritis secondary to treatment with PD-1/PD-L1 inhibitors." (PMID 39590170, 2024). "Further, patients with a DC ≤ 2.5 ms showed higher levels of inflammatory markers such as C-reactive protein (CRP) and procalcitonin (PCT), as well as leukocytosis, compared to patients with a DC > 2.5 ms." (PMID 38010539, 2024).